PSMB8 (proteasome 20S subunit beta 8)
Diseases named in the same sentence as PSMB8 in open-access papers (continued):
Sharing a sentence is not in itself a finding about the gene and the disease.
inflammatory bowel disease (4 papers, 2012 to 2022). A spectrum of small and large bowel inflammatory diseases of unknown etiology. "Genome-wide association studies (GWASs) in IgAN support that galactose-deficient IgA1 (Gd-IgA1) is heritable, and they also suggest that some GWAS loci, such as CARD9, TNFSF13, and PSMB8, are shared among IgAN, inflammatory bowel disease (IBD), and bacterial infections." (PMID 33436510, 2021). "PSMB8 and PSMB9 constitute interferon-inducible immunoproteasome mediating intestinal NF-κB activation in inflammatory bowel diseases (IBD)." (PMID 31888082, 2019).
non-small cell lung carcinoma (4 papers, 2021 to 2023). A group of at least three distinct histological types of lung cancer, including non-small cell squamous cell carcinoma, adenocarcinoma, and large cell carcinoma. "It is worth noting that KNTC1 may regulate non-small cell lung cancer through its downstream target PSMB8." (PMID 37480569, 2023).
Obesity (4 papers, 2013 to 2021). Accumulation of substantial excess body fat. "On the other hand, monocytes from mothers with obesity (n = 3/time point) exhibited suppression of genes involved in interferon signaling (STAT1, GBP5, PSMB8) and response to reactive oxygen species (STRBP, HEBP2, TRAP1, TRPA1) (p value <0.001) with gestational age." (PMID 34195568, 2021).
pancreatic cancer (4 papers, 2021 to 2025). "Meanwhile, CRISPR-based genetic ablation of LMP7 (gene name PSMB8) in the human pancreatic cancer cell line SW 1990 resulted in complete loss of LMP7 staining with EPR14482(B)." (PMID 40507366, 2025). "Thus, FAK-dependent regulation of Psmb8 and MHC-I is not universal across PDAC cell clones, even from the same tumour, suggesting that pancreatic cancer cell heterogeneity has the potential to impact FAK function." (PMID 36977556, 2023).
Stroke (4 papers, 2013 to 2024). Sudden impairment of blood flow to a part of the brain due to occlusion or rupture of an artery to the brain. "Interestingly, we found that the top 3 molecular targets of miR-451a (OSR1, CUX2, PSMB8) have been previously associated with stroke or studied in relation with brain damage." (PMID 35328807, 2022). "Stroke increased gene expression of the proinflammatory A1 astrocyte markers Serping1, Psmb8, Srgn, and Gbp2 in both normotensive and hypertensive mice (P < 0.05)." (PMID 38886874, 2024).
vitiligo (4 papers, 2017 to 2025). Generalized well circumscribed patches of leukoderma that are generally distributed over symmetric body locations and is due to autoimmune destruction of melanocytes. "The down-regulation of PSMB8 in patients with risk genotype ‘CC’ advocates the vital role of PSMB8 in the autoimmune basis of vitiligo." (PMID 28700671, 2017). "The frequency of ‘TT’ genotype of PSMB8 polymorphism was significantly lowered in patients with generalized and active vitiligo (p = 0.019 and p = 0.005) as compared to controls suggesting its association with the activity of the disease." (PMID 28700671, 2017). "In conclusion, the association of PSMB8 rs2071464 polymorphism with generalized and active vitiligo suggests defective antigen processing which might influence the peptide repertoire presented to the immune cells targeting melanocytes." (PMID 28700671, 2017). "Candidate gene studies highlight the role of autoimmunity in vitiligo, as polymorphisms in IL1B, IL4, PSMB8, NLRP1, NPY, FOXP3, and IFNG genes were found to be associated with vitiligo." (PMID 36164321, 2022). "Distribution of haplotypes frequencies for PSMB8 (C/T) and TAP1 (A/G) polymorphisms in vitiligo patients and controls." (PMID 28700671, 2017). "Association of PSMB8 and TAP1 polymorphisms in patients with active and stable vitiligo from Gujarat." (PMID 28700671, 2017). "Several studies have addressed the association of PSMB8 and TAP1 polymorphisms in patients with vitiligo; however, studies revealing the impact of these polymorphisms at transcript and protein levels are few." (PMID 28700671, 2017). "Our findings have recently been supported by the blood transcriptomics analysis of vitiligo patients which revealed significant down regulation of PSMB8 expression in patients." (PMID 28700671, 2017). "A significant decrease in expression of PSMB8 at both transcript level (p = 0.002) as well as protein level (p = 0.0460) was observed in vitiligo patients as compared to controls." (PMID 28700671, 2017). "Out of 8 different single nucleotide polymorphisms (SNPs) of PSMB and TAP gene region studied, PSMB8 intron 6 G/T and TAP1 exon 10 A/G were found to be significantly associated with vitiligo in the Western population." (PMID 28700671, 2017). "Another study showed significant association of TAP1 exon 10 A/G polymorphism with vitiligo in Saudi population but not for PSMB8 intron 6 G/T polymorphism." (PMID 28700671, 2017). "In addition, another recent study has demonstrated the IFN-γ induced lower expression of PSMB8 in PBMCs of vitiligo patients as compared to controls." (PMID 28700671, 2017). "PSMB8 polymorphism in addition to previously reported susceptibility loci such TNFA, TNFB, IL1B, IFNG, NALP1, IL4 etc. demonstrate immunogenetic predisposition in vitiligo patients from Gujarat." (PMID 28700671, 2017). "Furthermore, the decreased transcript expression of PSMB8 in patients with vitiligo was confirmed at protein level by western blot analysis in PBMCs of healthy controls (n = 6) and patients with active GV (n = 7)." (PMID 28700671, 2017). "Association of PSMB8 and TAP1 polymorphisms in patients with vitiligo from Gujarat." (PMID 28700671, 2017). "However, despite having high prevalence of vitiligo in Gujarat, there are no reports of PSMB8 and TAP1 polymorphisms so far." (PMID 28700671, 2017). "However, further replicative studies and in vitro functional studies for PSMB8 and TAP1 are needed to delineate the role of defective antigen processing and presentation pathways in vitiligo pathogenesis." (PMID 28700671, 2017).
atopic dermatitis (3 papers, 2021 to 2025). "PSMB8 has been identified as a direct target of miR-451a, implicating its involvement in childhood atopic dermatitis and neuronal differentiation in mice." (PMID 40334200, 2025). "It would also be interesting to check if a PSMB8 blockade could diminish inflammation in psoriatic and atopic dermatitis lesions." (PMID 39273140, 2024). "The main objective of our work was to differentiate between healthy skin (C), atopic dermatitis (AD) and psoriasis vulgaris (PV) biopsies on the base of involucrin (IVL) and human β-defensin-2 (hBD-2) concentrations and their mRNA, as well as mRNA for TPP2 and PSMB8." (PMID 39273140, 2024).
bladder cancer (3 papers, 2020 to 2023). "The present study exploited a variety of bioinformatic analyses to identify the PSMB8/PSMB9 immunoproteasomes and their co-expressed genes, which may be supported for the early diagnosis and prevention of bladder carcinoma." (PMID 36937130, 2023).
hepatocellular carcinoma (3 papers, 2022 to 2025). A malignant tumor that arises from hepatocytes. "Previous studies have shown that PSMB8 plays an important role in hepatocellular carcinoma through interactions with zinc finger family proteins." (PMID 41228214, 2025). "In hepatocellular carcinoma, PSMB8 was found to be co-expressed with zinc finger protein 655 a protein that supports cancer proliferation and tumour establishment and PSMB8 knock-down significantly reduced disease severity." (PMID 40698074, 2025). "Aberrant expression of members of the proteasome subunit beta (PSMB) family (including PSMB2, PSMB4, PSMB7 and PSMB8) has been reported in hepatocellular carcinoma (HCC)." (PMID 36062301, 2022).
lung adenocarcinoma (3 papers, 2020 to 2025). A carcinoma that arises from the lung and is characterized by the presence of malignant glandular epithelial cells. "Furthermore, high expression of PSMB8 was associated with poor survival in LAML and lung adenocarcinoma (LUAD)." (PMID 34650125, 2021). "The only gene in this group of immune response genes that has been previously identified as being differentially expressed between wild type and ρ0 tumor cells is PSMB8, but in this case, it was more highly expressed in A549ρ0 cells than in A549 human lung adenocarcinoma cells." (PMID 33329014, 2020).
myositis (3 papers, 2014 to 2025). "Relative quantification of proteasomal subunit expression by real time RT-PCR revealed a myositis related significant increase of at least one of the immunoproteasomal subunits PSMB8, PSMB9 and/or PSMB10 in all investigated cellular subsets except CD4+." (PMID 25098831, 2014). "Comparison with reference profiles of sorted immune cells and healthy muscle confirmed upregulation of PSMB8 and -9 in myositis biopsies beyond infiltration related changes." (PMID 25098831, 2014). "Despite we observed a generalized overexpression of PSMB8, whose transcription has been associated to type-II IFN exposure, in all three comparisons between myositis and NDC conditions, IFNG was downregulated in DM compared to NDC and upregulated in irMyositis compared to DM." (PMID 40759686, 2025).
renal cell carcinoma (3 papers, 2020 to 2023). "Psmb9 and Psmb8 are genes encoding immunoproteasome subunits that act upstream or within antigen processing, bacterial presentation, and response, and have been implicated in both lymphoma and renal cell carcinoma." (PMID 37193034, 2023). "PSMB8 expression was found to be upregulated in all histological sub-types of renal cell carcinoma." (PMID 34944095, 2021).
small cell lung carcinoma (3 papers, 2021 to 2023). Small cell lung cancer (SCLC) is a highly aggressive malignant neoplasm, accounting for 10-15% of lung cancer cases, characterized byrapid growth, and early metastasis. "In both NSCLC and small cell lung cancer (SCLC), acquisition of cisplatin resistance correlated with increased expression of PSMB8 and PSMB9." (PMID 34944095, 2021).
gastric adenocarcinoma (2 papers, 2016 to 2021). "Consistent with the association between nuclear PSMB8 expression and gastric adenocarcinoma aggressiveness, the patient group survival rate decreased as nuclear PSMB8 expression increased." (PMID 26894977, 2016). "Regarding cytoplasmic PSMB8 expression, - (240/385, 62.3%), + (104/285, 27.0%), and ++ (41/385, 10.6%) were observed in gastric adenocarcinoma cells." (PMID 26894977, 2016). "We investigated the clinicopathological and prognostic significance of nuclear PSMB8 expression in 385 cases of gastric adenocarcinoma." (PMID 26894977, 2016). "PSMB8 expression was identified in the cytoplasm and nuclei of gastric adenocarcinoma cells." (PMID 26894977, 2016).
gynecological cancers (2 papers, 2022 to 2023). "Interestingly, hierarchical clustering revealed two main clusters of PSM genes, of which one cluster contained five PSM genes (PSMB8-10 and PSME1-2) with high expression in a number of urologic, CNS, and gynecological cancers." (PMID 36123629, 2022).
lung squamous cell carcinoma (2 papers, 2021 to 2025). "PSMB8 was overexpressed in tumor tissues compared to normal tissues on average, except for lung squamous cell carcinoma (LUSC) and adrenocortical carcinoma." (PMID 34650125, 2021).
microcytic anemia (2 papers, 2025). Anemia in which the red blood cell volume is decreased. "PSMB8 also has a significant impact on myatrophy, arthrogryposis, panniculitis-associated lipodystrophy syndrome, and microcytic anemia." (PMID 40335825, 2025).
partial lipodystrophy (2 papers, 2016 to 2022). Loss and redistribution of subcutaneous and/or visceral adipose tissue from specific regions of the body. "Since patients with PRAAS develop partial lipodystrophy and Psmb8-deficient mice show reduced adipose tissue weight with high-fat diet feeding, we fed control and Psmb8-KI mice a normal diet and measured their body weight from 4–16 weeks old." (PMID 35393946, 2022). "The PSMB8 mutation in JASL causes partial lipodystrophy especially in the upper or lower extremities." (PMID 27225296, 2016).
sarcoidosis (2 papers, 2015 to 2016). Sarcoidosis is a multisystemic disorder of unknown cause characterized by the formation of immune granulomas in involved organs. "They demonstrated increased immunoreactivity of PSMB8 and PSMB9 in sarcoidosis lungs, primarily in epithelial cells and granulomas." (PMID 27460362, 2016).
thyroid (2 papers, 2020 to 2025). "Some of miR-451 downstream targets are well known to be involved in the control of invasive properties of thyroid and others cancers: MIF and PSMB8." (PMID 32824921, 2020).
Blau syndrome (1 paper, 2021). Blau syndrome (BS) is a rare systemic inflammatory disease characterized by early onset granulomatous arthritis, uveitis and skin rash. "In parallel, we transduced control human ES cells with the PSMB8 mutation gene and generated two pairs of pluripotent stem cells that are genetically uniform except for the difference in PSMB8 genotype, as in the case of Blau syndrome." (PMID 33535645, 2021).
breast tumors (1 paper, 2025). "No evident difference in expression of PSMB1-10 genes in breast tumors compared to other tumor types was revealed; however, we detected that BC cell lines were much more dependent on PSMB8 expression." (PMID 39796785, 2025).
cholangiocarcinoma (1 paper, 2021). A carcinoma that arises from the intrahepatic biliary tree (intrahepatic cholangiocarcinoma) or from the junction, or adjacent to the junction, of the right and left hepatic ducts (hilar cholangiocarcinoma). "In contrast, there seemed to be no immune infiltration-associated expression patterns with PSMB8 in cholangiocarcinoma (CHOL) and rectum adenocarcinoma (READ)." (PMID 34650125, 2021).
chordoma (1 paper, 2023). Chordomas are rare malignant tumors arising from embryonic remnants of the notochord in axial skeleton. "Our data show a significant increased expression for both PSMB5 and PSMB8 subunits in these two chordoma cells compared to both HEK-293 and HUVEC cells." (PMID 37111759, 2023). "For the first time, we performed the gene expression analysis for proteasomal subunits PSMB5 and PSMB8, and found that these two subunits are increased in chordoma." (PMID 37111759, 2023). "Furthermore, we found that proteasomal subunits proteasome 20S subunit beta 5 (PSMB5) and proteasome 20S subunit beta 8 (PSMB8) upregulated in two human chordoma cell lines, U-CH1 and U-CH2." (PMID 37111759, 2023). "Proteasomal subunits PSMB5 and PSMB8 are highly upregulated in chordoma cell lines U-CH1 and U-CH2: As we found, proteasomal inhibitors as one class of the hits from primary screening; next, we asked whether proteasomal subunits are increased in chordoma." (PMID 37111759, 2023). "Furthermore, we discovered that proteasomal subunits PSMB5 and PSMB8 are increased in human chordoma cell lines U-CH1 and U-CH2, confirming that the proteasome may serve as a molecular target whose specific inhibition may lead to better therapeutic strategies for chordoma." (PMID 37111759, 2023).
Cirrhosis (1 paper, 2022). A chronic disorder of the liver in which liver tissue becomes scarred and is partially replaced by regenerative nodules and fibrotic tissue resulting in loss of liver function. "We could observe that the A1 subtype-related markers (FKBP5, GBP2, PSMB8, and SRGN) were remarkably elevated in HE samples compared to healthy control samples and cirrhosis samples." (PMID 36424620, 2022).
coronary artery disease (1 paper, 2021). "In coronary artery disease (CAD), patients present with decreased expression of PSMB8." (PMID 33924425, 2021).
demyelination (1 paper, 2023). "Future work should also investigate neuronal expression of antigen-processing genes, such as PSMB8 and TAP2, during acute inflammatory demyelination." (PMID 37676734, 2023).
dermatitis (1 paper, 2022). An inflammatory process affecting the skin. "Psmb8-KI mice showed higher susceptibility to imiquimod-induced skin inflammation (IMS)." (PMID 35393946, 2022). "As we did not detect any signs of spontaneous inflammation in Psmb8-KI mice even after 6 months of age (data not shown), we tested the sensitivity to imiquimod-induced dermatitis (IMS)." (PMID 35393946, 2022).
Ebola (1 paper, 2025). "Correspondingly, antigen presentation ISGs (HLA-B, PSMB8, PSMB9, and TAP1102) were not markedly induced by Ebola, although they were upregulated in response to other viruses." (PMID 41279810, 2025).
Erythema (1 paper, 2023). Redness of the skin, caused by hyperemia of the capillaries in the lower layers of the skin. "Autosomal recessive loss-of-function (LOF) mutations in the proteasome subunit beta type 8 (PSMB8) cause Nakajo-Nishimura syndrome (NNS) with nodular erythema, elongated and thickened fingers, and emaciation, and CANDLE." (PMID 37087470, 2023).
Hepatic steatosis (1 paper, 2023). Steatosis is a term used to denote lipid accumulation within hepatocytes. "Thus an upregulation of the components of the proteasome complex PSMA2 and PSMB8, in the presence of HK4 might lead to proper protein degradation and avoid accumulation of misfolded proteins, which could otherwise cause hepatic steatosis." (PMID 36860523, 2023).
hepatitis B (1 paper, 2019). "Cg08331398 maps to the PSMB8 gene and has been associated with several types of cancer and hepatitis B." (PMID 30215712, 2019).
hyperlipidaemia (1 paper, 2025). "The results indicated that patients with hyperlipidaemia had significantly lower levels of HDLC and PSMB8 expression than the normal group, with a statistically significant difference (p < 0.05)." (PMID 39789419, 2025).
idiopathic inflammatory myopathies (1 paper, 2022). "Previous research reported that PSMB8, PSMB9 and PSMB10 expressed at significantly abundant levels in dendritic cells, monocytes, and CD8+ T-cells in idiopathic inflammatory myopathies, which correlated highest with STAT1, IRF1 and IFN-γ expression." (PMID 35933405, 2022).
Immunodeficiency (1 paper, 2026). Failure of the immune system to protect the body adequately from infection, due to the absence or insufficiency of some component process or substance. "Together, our data show that monoallelic PSMB8 variants disrupt immunoproteasome assembly, resulting in clinically variable disease with immunodeficiency and systemic inflammation." (PMID 42167218, 2026).
inflammatory skin disease (1 paper, 2024). Inflammatory skin disorders covers a broad category that includes many conditions ranging in severity, from mild itching to grave medical health complications These disorders are common in people of all ages and races. "No other correlation was found among IVL, hBD-2, IVL mRNA, hBD-2 mRNA, TPP2 mRNA and PSMB8 mRNA, neither in the patients with inflammatory skin diseases nor in the control group." (PMID 39273140, 2024).
juvenile dermatomyositis (1 paper, 2014). Juvenile dermatomyositis (JDM) is the early-onset form of dermatomyositis (DM), a systemic, autoimmune inflammatory muscle disorder, characterized by proximal muscle weakness, evocative skin lesion, and systemic manifestations. "Reanalysis of muscle transcriptomes from 12 different muscle diseases (GSE3307) with non-inflammatory myopathies except from juvenile dermatomyositis (JDM) revealed upregulation of PSMB8/-9 only in samples from JDM and in one out of four samples from limb girdle muscular dystrophy 2I (LGMD2I)." (PMID 25098831, 2014).
myocardial infarction (1 paper, 2024). Gross necrosis of the myocardium, as a result of interruption of the blood supply to the area, as in coronary thrombosis. "Here, we found that the expression level and activity of Psmb8 were significantly reduced in the heart of I/R mice and in subjects with myocardial infarction (MI)." (PMID 39516219, 2024). "To identify whether decreased Psmb8 expression also appears in human with myocardial infarction (MI), we further analyzed published single-nucleus RNA sequencing (snRAN-seq) data." (PMID 39516219, 2024).